CENPA (centromere protein A)
Diseases named in the same sentence as CENPA in open-access papers (continued):
Sharing a sentence is not in itself a finding about the gene and the disease.
prostate carcinoma (15 papers, 2020 to 2025). A carcinoma that arises from epithelial cells of the prostate gland. "In prostate cancer, centromeric histone H3 variant centromere protein A (CENPA) mRNA expression correlates significantly with MKI67 gene expression." (PMID 34073937, 2021). "Gain-of-function and loss-of-function experiments confirmed that CENPA promotes prostate cancer cell line growth." (PMID 32371391, 2020). "In conclusion, we show here that the much-studied centromeric histone H3 variant CENPA is markedly overexpressed in a wide panel of patients with prostate cancer, and overexpression correlates with disease progression." (PMID 32371391, 2020). "We thus first conducted a comparative analysis of CENPA expression relative to the remaining transcriptome in prostate cancer to identify associations with biological concepts that could computationally guide functional assessments." (PMID 32371391, 2020). "Taken together, CENPA expression is strongly linked to gene signatures that underlie processes that govern proliferation, cell cycle progression, and centromere/kinetochore integrity in prostate cancer." (PMID 32371391, 2020). "The overexpression of CENPA in prostate cancer has been demonstrated by a study with both in vivo and in vitro evidence." (PMID 39820192, 2025). "In ovarian, hepatocellular and prostate cancers, CENPA functions as a promoter of tumor growth, proliferation and migration." (PMID 35816352, 2022). "CDC25C, CDCA5, TOP2A, and CENPU, genes whose expression levels were strongly correlated to CENPA expression in prostate cancer tissue, were all notably down-regulated with CENPA depletion, as well as bound by CENPA." (PMID 32371391, 2020). "We thus correlated CENPA mRNA levels to the expression levels of all other protein coding elements (Data Set S1) to deconvolute its relative contribution to prostate cancer progression." (PMID 32371391, 2020). "We additionally used the Database for Annotation, Visualization, and Integrated Discovery (DAVID) to conduct ontology assessments on the highest-performing genes from our transcriptome-wide correlation against CENPA expression in prostate cancer (r > 0.8)." (PMID 32371391, 2020). "Of note, we observed that EZH2 expression indeed tracked tightly with CENPA expression in prostate cancer tissue." (PMID 32371391, 2020). "Although CENPA overexpression is rather ubiquitous across cancer types, it possible that differential gene expression seen in prostate cancer with CENPA modulation is tissue-specific." (PMID 32371391, 2020). "Supporting this idea, recent data show that CENPA is required for the transcription of genes involved in cell proliferation and consistently, CENPA overexpression drives proliferation in prostate cancer cells." (PMID 33167489, 2020). "Although we show here that prostate cancer tissue and cell lines overexpress CENPA, previous work suggests that occupation of only ∼4% of the α-satellite rich centromere is sufficient for producing functional centromeres." (PMID 32371391, 2020). "CENPA expression tracks tightly with a number of previously identified prostate cancer pathogenesis factors including CENPF, UBE2C, and EZH2 (and Data Set S1)." (PMID 32371391, 2020). "Although its role in the centromere is certainly vital, we now posit that ectopic deposition of CENPA in prostate cancer plays an additional role in modulating cell division by regulating critical proliferation, cell cycle, and centromere/kinetochore genes." (PMID 32371391, 2020). "CENPA depletion in prostate cancer cells results in an accumulation of cells in G1 that seem to be unable to progress through the cell cycle." (PMID 32371391, 2020). "We verified robust overexpression of CENPA in prostate cancer cell lines, as compared with benign prostatic epithelial lines." (PMID 32371391, 2020).
prostate carcinoma (continued). "Taken together, our data show that CENPA is an essential factor for progression through the cell cycle and that overexpression drives proliferation of prostate cancer cells." (PMID 32371391, 2020). "CENPA was found to be highly overexpressed in both prostate cancer tissue and cell lines." (PMID 39456925, 2024). "Indeed, our data show that HJURP, the chaperone that directs CENPA to centromeric DNA, demonstrates strong concordance with CENPA expression in prostate cancer tissue." (PMID 32371391, 2020). "Taken together, our findings show that CENPA overexpression is crucial to prostate cancer growth." (PMID 32371391, 2020). "The ubiquitous nature of CENPA overexpression in other malignancies, in addition to prostate cancer, suggests that CENPA and factors downstream in its signaling pathway might be targeted for therapeutic purposes." (PMID 32371391, 2020). "We suggest for the first time that CENPA mislocalization may have functional consequences through an unexpected role as a regulator of gene expression in prostate cancer." (PMID 32371391, 2020). "Given prior reports of ectopic deposition in the setting of CENPA overexpression and the marked overexpression of CENPA in prostate cancer, we performed native ChIP followed by sequencing to identify noncentromeric and potentially regulatory binding sites for CENPA in prostate cancer." (PMID 32371391, 2020). "The abundance of CENPA in prostate cancer raised the question of whether overexpression plays a functional role in disease pathogenesis and progression." (PMID 32371391, 2020). "It is thus conceivable that either HJURP or DAXX carries out a chaperone like function for CENPA in prostate cancer, although re-ChIP assays involving CENPA and HJURP together or CENPA and DAXX together would be necessary to prove the presence of such a mechanism." (PMID 32371391, 2020). "Further, CENPA is vital to the growth of prostate cancer cells and likely has a previously uncharacterized function as an epigenetic regulator of transcriptional activity involving genes important for proliferation, cell cycle progression, and centromere and kinetochore integrity in prostate cancer." (PMID 32371391, 2020). "Interestingly, CENPA appears to affect proliferation of prostate cancer cells by acting as a transcriptional regulator that modulates expression of genes critical to proliferation, cell cycle progression, and centromere/kinetochore integrity in addition to its role in the centromere." (PMID 32371391, 2020). "Work in HeLa cells additionally suggests that overexpressed CENPA is directed to gene regulatory elements through interaction with DAXX, a protein that has been previously been shown to be overexpressed in prostate cancer." (PMID 32371391, 2020). "CENPA depletion led to a profound growth-inhibitory effect on 22Rv1, LnCaP, and DU145 prostate cancer cells." (PMID 32371391, 2020). "Here we report that CENPA is highly overexpressed in prostate cancer (PCA) and that disease progression correlates with CENPA expression within a large patient cohort." (PMID 32371391, 2020). "Strong associations with cellular proliferation genes and select pathogenesis factors independent of AR implicate CENPA as a contributor to a biological process that is involved in androgen refractory prostate cancer progression." (PMID 32371391, 2020). "CENPA-directed ChIP-seq identified 569 noncentromeric binding sites in the VCaP prostate cancer cell line within three experimental replicates (and Data Set S2)." (PMID 32371391, 2020). "Intriguingly, AR signaling, the most commonly targeted and mutated molecular signature in metastatic castration–resistant prostate cancer, was not captured by a CENPA-focused analysis, a finding that we further confirmed in tissue culture experiments." (PMID 32371391, 2020).
prostate carcinoma (continued). "CENPA knockdown markedly decreases proliferation of prostate cancer cells but not that of benign prostate cells and increased expression of CENPA causes benign prostate epithelial cells to proliferate more rapidly." (PMID 32371391, 2020). "Prostate cancer (PRAD) and sarcoma (SARC) were shown earlier in this study to overexpress CENPA, while osteosarcoma was not included among the cancer types in the TCGA data set." (PMID 39820192, 2025).
colon cancer (11 papers, 2009 to 2024). "CENPA overexpression was observed in a high number of aneuploid colon cancers." (PMID 20003272, 2009). "CENPA acts as an upstream transcriptional activator of the karyopherin α2 subunit gene (KPNA2), indirectly promoting tumor cell growth and glycolysis in patients with colon cancer." (PMID 35938165, 2022). "And CENPA can recruit histone acetyltransferase (HAT) general control of amino acid synthesis (GCN)-5 to the karyopherin α2 subunit gene (KPNA2) promoter region to epigenetically activate its transcriptional activity, resulting in glycolysis and malignant growth in colon cancer (CC) cells." (PMID 37457582, 2023).
ovarian carcinoma (11 papers, 2013 to 2025). A malignant neoplasm originating from the surface ovarian epithelium. "Overexpression of CENPA was demonstrated to be associated with poor clinical outcomes of ovarian cancer patients." (PMID 26587348, 2015). "In ovarian cancer, CENPA was found associated with the proliferation of cancer cells and survival of patients, which might be directly regulated by the MYBL2." (PMID 39820192, 2025). "Next, we further investigated the positive correlation between OIP5 and CENPA in ovarian cancer by GEPIA." (PMID 37660035, 2023). "As previously reported, the transcription factor CENPA mediates an important role for MYBL2 in ovarian cancer cell proliferation." (PMID 36601328, 2022). "To date, many reports have shown a link between CENPA and various human cancers, including ovarian cancer." (PMID 26587348, 2015). "The ablation of CENPA inhibited cell proliferation in ovarian cancer." (PMID 36741311, 2023). "Recently, the overexpression of CENPA was also identified in several human malignancies, including hepatocellular carcinoma, colorectal cancer, lung adenocarcinoma, breast cancer, and ovarian cancer." (PMID 26587348, 2015).
osteosarcoma (10 papers, 2011 to 2025). A usually aggressive malignant bone-forming mesenchymal neoplasm, predominantly affecting adolescents and young adults. "CENPA (centromere protein A), a histone H3 variant, is highly expressed in cancers, including breast, colorectal, liver, lung, ovarian, and osteosarcoma." (PMID 30886771, 2019). "AURKA and CENPA had, respectively, been identified as a susceptibility gene and an independent poor prognostic factor for osteosarcoma." (PMID 26337976, 2015). "In addition, the median survival time was significantly longer in patients with low-CENPA expression osteosarcomas than in those with high-CENPA expression osteosarcomas." (PMID 26337976, 2015). "FOXM1 controls transcription of the mitotic regulatory genes Cdc25B, Aurora B kinase, survivin, centromere protein A (CENPA), and CENPB in both mouse embryonic fibroblasts (MEFs) and human osteosarcoma." (PMID 31968679, 2020). "Although we did not see observable changes in the number of CENPA foci or their localization after HU in human osteosarcoma cells, this could be a consequence of different types of damage (i.e. HU versus IR/laser) as we did see more robust recruitment of CENPA throughout the nucleus." (PMID 25898113, 2015).
glioma (9 papers, 2015 to 2025). A benign or malignant brain and spinal cord tumor that arises from glial cells (astrocytes, oligodendrocytes, ependymal cells). "The prognostic association between CENPA and glioma patient survival was supported by five independent glioma datasets, with sample sizes of 703, 693, 325, 301, and 120, respectively." (PMID 39820192, 2025). "KM survival analysis showed that low CENPA expression was associated with a better prognosis in patients with glioma." (PMID 36341103, 2022). "It was suggested that CENPA was highly implicated in immune infiltration and the formation of multiple components in gliomas." (PMID 36341103, 2022). "In general, these findings revealed that CENPA was associated with immune cell infiltration, immune score, and immune checkpoints in patients with glioma." (PMID 36341103, 2022). "Transcription factors such as Snail, Slug and Twist were significantly associated with CENPA, which might enhance the invasive migration ability of glioma, adversely affecting the prognosis." (PMID 39620895, 2024). "A strong correlation with numerous glioma prognostic risk factors suggests that CENPA may play an important role in glioma progression." (PMID 36341103, 2022). "The results of univariate and multivariate Cox analyses showed that CENPA was a high-risk factor and could be used as an independent prognostic indicator in patients with glioma." (PMID 36341103, 2022). "Multivariate Cox analysis revealed that CNEPA (HR = 1.344; 95% CI = 1.228–1.472; p < 0.001) was independently associated with overall survival, suggesting that CENPA could serve as an independent prognostic indicator for glioma." (PMID 36341103, 2022). "In this study, we developed strategies for applying CENPA in glioma prognosis, illustrating its potential as a clinical prognostic biomarker for cancer." (PMID 39820192, 2025). "To demonstrate the practicable clinical application of CENPA, we focused on one cancer type, glioma, where CENPA was demonstrated to have promising prognostic value." (PMID 39820192, 2025). "Univariate Cox regression results indicated that CENPA level, 1p/19q codeletion, primary therapy outcome, IDH status, and age were significantly associated with overall survival in glioma patients." (PMID 39820192, 2025). "In glioma, CENPA demonstrated reliable prognostic potential when used alongside other prognostic factors." (PMID 39820192, 2025). "To identify variables for the CENPA-based prognostic model in glioma patients, we performed Cox regression analysis to evaluate prognostic factors." (PMID 39820192, 2025). "In this context, this study combined LGG and GBM and analyzed the prognostic value of CENPA for overall glioma." (PMID 39820192, 2025). "Through analysis of TCGA, Rembrandt and CGGA databases, we discovered a close and statistically significant relationship between EZH2 and CENPA in glioma of all grades." (PMID 39620895, 2024). "Given the significant role of CENPA in cancer biology, we aim to explore the function of CENPA, to better understand its potential role in glioma." (PMID 39620895, 2024). "Considering the important role of CENPA in centromere proteins and its current progress in glioma, we chose to further study CENPA." (PMID 39620895, 2024). "Analysis of data from TCGA and CGGA revealed a gradual upregulation of CENPA gene expression with increasing glioma grade (p < 0.001)." (PMID 39620895, 2024). "Through immunohistochemistry (IHC) and western blot experiments, we found that CENPA was upregulated in glioma, with a significant difference observed statistically (p < 0.001)." (PMID 39620895, 2024). "The scratch assay, edu, cck8, flow cytometry and transwell after CENPA knockdown or overexpression had significant effects on the functions of glioma." (PMID 39620895, 2024). "Machine learning based on cancer functional state helps to combine multi‐omics methods to screen for key gene, such as CENPA, that influences the phenotype of glioma and patients' prognosis." (PMID 39620895, 2024).
glioma (continued). "Within 24 h of knocking down CENPA, glioma cells showed significant cell death, with both early and late apoptosis occurring, and a higher proportion of early apoptosis (p < 0.05)." (PMID 39620895, 2024). "In glioma, CENPA is positively correlated with WHO grading at both the gene and protein levels, and high CENPA affects patients' poor prognosis." (PMID 39620895, 2024). "We used TCGA TARGET GTEx cohort downloaded from UCSC Xena to evaluate CENPA expression in the glioma and normal tissue samples." (PMID 36341103, 2022). "The relationship between the expression and prognostic value of the CENPA gene in glioma was investigated by Kaplan–Meier (KM) survival analysis with RNA-seq and clinical profiles downloaded from the Chinese Glioma Genome Atlas (CGGA) and UCSC Xena." (PMID 36341103, 2022). "A heatmap was constructed showing the top 100 genes co-expressed with CENPA based on the Pearson correlation coefficient in glioma." (PMID 36341103, 2022). "The Kaplan–Meier survival analysis of the CGGA dataset (including GBM and LGG) revealed that the lower the expression of CENPA, the better the prognosis of patients with glioma." (PMID 36341103, 2022). "Previous studies have revealed a significant correlation between CENPA and the survival of patients with glioma." (PMID 36341103, 2022). "The differential expression of CENPA among the glioma and normal tissues was further validated using the gene expression information extracted from GSE4290 and GSE16011." (PMID 36341103, 2022). "Meanwhile, qPCR results of patients with gliomas from our hospital also validated the differential expression of CENPA in normal brain tissues compared with glioma tissues." (PMID 36341103, 2022). "The GEPIA website, The Cancer Genome Atlas, and the Gene Expression Omnibus (GEO) were used to assess the expression of CENPA in glioma." (PMID 36341103, 2022). "An additional important finding in this study is that the expression of CENPA correlated with the degree of immune infiltration in glioma." (PMID 36341103, 2022). "Scatter plots and bubble plots showed that MKI67 and CENPA were mainly co-expressed in glioma and stromal cells, which revealed that CENPA-expressing cells showed high proliferation." (PMID 36341103, 2022). "Taken altogether, the results revealed that CENPA expression is upregulated in glioma and can be used as a prognostic marker and potential therapeutic target in patients with glioma." (PMID 36341103, 2022). "The expression of CENPA in glioma and normal tissue samples was evaluated using the GEPIA website, and the result revealed that CENPA was significantly expressed in both LGG and GBM tissues." (PMID 36341103, 2022). "Then, using data downloaded from the CGGA database, we performed a KM survival analysis to confirm CENPA prognostic efficacy in different glioma subgroups." (PMID 36341103, 2022). "Meanwhile, we also analyzed the relationship between CENPA and the clinical characteristics of patients with glioma." (PMID 36341103, 2022). "Furthermore, we developed strategies for the application of CENPA in glioma prognosis as an example of the future development of CENPA as a clinical cancer biomarker." (PMID 39820192, 2025). "Latest study shows that CENPA promotes stemness in glioma stem cells." (PMID 40612514, 2025). "Additionally, a prognostic model for glioma patients was developed to demonstrate CENPA’s potential as a biomarker." (PMID 39820192, 2025). "It has been shown that CENPA could interfere with the normal progression of mitosis and regulate the tumor immune microenvironment favoring glioma development." (PMID 38681202, 2024). "To further investigate the mechanism of CENPA in glioma, we searched for transcription factors that might bind to CENPA and found Enhancer of Zeste Homologue 2 (EZH2)." (PMID 39620895, 2024). "This implied that research in the future could explore multiple directions to further elucidate the relationship between CENPA and glioma." (PMID 39620895, 2024).